LINC02027 (long independently transcribed non-coding RNA 2027)
Synonyms: LOC728290
Gene: Long non-coding RNA gene on chromosome 3 (80,993,770 to 81,105,182, forward strand). Ensembl gene ENSG00000243694.
Diseases named in the same sentence as LINC02027 in open-access papers:
LINC02027 is named in the same sentence as 1 disease in open-access papers, as found by Europe PMC text mining. Sharing a sentence is not in itself a finding about the gene and the disease. The quoted sentences say what the papers report.
tumor (1 paper, 2022). "LncRNA U62317.1, MIR193BHG, AC121338.2, and LINC02027 were highly expressed in tumor cells, while AC156455.1 showed the opposite trend." (PMID 35860590, 2022).